ACSL1 (acyl-CoA synthetase long chain family member 1)
Diseases named in the same sentence as ACSL1 in open-access papers (continued):
Sharing a sentence is not in itself a finding about the gene and the disease.
cardiovascular disease (2 papers, 2025). "Downregulation of ACSL1 mitigates the pro-inflammatory effects of palmitic acid (PA), thereby alleviating inflammation in cardiovascular disease." (PMID 41288931, 2025). "The role of ACSL1 in cardiovascular disease remains somewhat ambiguous." (PMID 41288931, 2025). "In conclusion, the role of ACSL1 in cardiovascular disease remains to be fully elucidated, including whether it functions as a protective factor, a risk factor, or a bidirectional regulator." (PMID 41288931, 2025).
nervous system diseases (2 papers, 2021 to 2024). "ACSLs (ACSL1, 3, 4, 5, and 6) are a family of CoA synthetases that activate long-chain FAs into acyl-CoA for the synthesis of cellular lipids and are thought to affect cell proliferation, including in nervous system diseases." (PMID 38609948, 2024).
adenocarcinoma (1 paper, 2024). A common cancer characterized by the presence of malignant glandular cells. "In primary lung tumors, a higher expression of ACSL1, ACSL4, and ACSL5 was significantly correlated with adenocarcinoma (ADC)." (PMID 38539505, 2024).
ACSL1 also shares sentences with these, for which no sentence is quoted: metabolic disease (5 papers); autoimmune disease (2); melanoma (2); osteoarthritis (2); prostate tumors (2); rheumatoid arthritis (2); adenovirus infection (1); Alcohol Use Disorder (1); bacterial infection (1); bipolar disorder (1); cataract (1); cryptococcosis (1); E. coli infection (1); esophageal adenocarcinoma (1); esophageal squamous cell carcinoma (1); fungal infection (1); glioblastoma (1); graft-vs.-host disease (1); Hypercholesterolemia (1); infectious disease (1); inflammation (1); injury (1); ischemic stroke (1); legionellosis (1); leishmaniasis (1); lipodystrophy (1); male fertility (1); metastatic tumors (1); morbid obesity (1); muscular atrophy (1).
A further 10 diseases each share a sentence with ACSL1 in 1 paper.